CD4 (CD4 molecule)
Diseases named in the same sentence as CD4 in open-access papers (continued):
Sharing a sentence is not in itself a finding about the gene and the disease.
cancer (continued). "Adoptive cell transfer (ACT) of CD4+ helper T cells has shown promise in cancer immunotherapy." (PMID 33809259, 2021). "CD4+ T cell responses are crucial for inducing and maintaining effective anticancer immunity, and the identification of human leukocyte antigen class II (HLA-II) cancer-specific epitopes is key to the development of potent cancer immunotherapies." (PMID 33592498, 2021). "Some interleukins were also detected in media from CD4+ T cells co-cultured with cancer cells." (PMID 34439305, 2021). "Some level of GITR expression may be a common feature between human cancers and murine models of adenovirus where cytotoxic CD4+ T cells are induced." (PMID 34910940, 2021). "In contrast to effector CD4+ T cells (Th1, Th2, Th17, and Tfh) that activate other immune cells, Treg cells are inherently suppressive, and considered to have a detrimental role in cancer by suppressing the antitumor immune response." (PMID 34868011, 2021). "Here we highlight that blocking the PSGL-1 pathway on CD4+ T cells may represent a new cancer therapy approach to eradicate tumors." (PMID 33708224, 2021). "Additionally, the genes encoding glycolysis enzymes were found to be misregulated (mostly downregulated) in CD4+ T cells grown with cancer cells compared to controls." (PMID 34439305, 2021). "Cancer exosomes inhibit the cytotoxic of CD4+ T cells, CD8+ T cells, and NK cells." (PMID 34062992, 2021). "CD4+ T cells play an important role in the immune response against cancer and infectious diseases." (PMID 34853796, 2021). "We were able to recompilate promising regulatory components and mechanisms of Th17 and Tregs differentiation under normal conditions, which we then connected with biological evidence in the context of the TME to better understand CD4 + T cell behavior in cancer." (PMID 34026764, 2021). "In cancer, Tregs accumulation could occur through different mechanisms, such as expansion of pre-existing Tregs or conversion of conventional CD4+T cells into Tregs." (PMID 33854498, 2021). "Additionally, research into a universal cancer vaccine examined the efficacy of stimulating CD4+ TH1 responses through vaccination with promiscuous epitopes from surviving and telomerase proteins." (PMID 34012451, 2021). "In the SKCM metastasis cohort, the increase in the amount of CD8+ T cells and activated CD4+ memory T cells may have more potential to kill cancer cells after undergoing anti-PD-1 immunotherapy." (PMID 33911146, 2021). "Thus, the assessment of anti-TERT CD4 Th1 cell immunity in circulating lymphocytes has been used as a tool for monitoring antitumor CD4 Th1 response in cancer patients." (PMID 34144673, 2021). "This raises three interesting questions that could potentially open up new approaches towards more effectively incorporating CD4+ T cells into the cancer immunotherapy arsenal." (PMID 32457487, 2021). "A comprehensive overview of the CD4+ TH cells, as discussed in this review, will help to elucidate the framework of CD4+ TH function and highlight the clinical relevance of harnessing CD4+ TH cells in cancer immunotherapy to encourage future translational research." (PMID 34012451, 2021). "To investigate the role of LSD1 in T cell immunity in the cancer context, we generated T cell-specific Lsd1 knockout (Cd4-Cre+Lsd1f/f) mice, which showed largely unaltered αβ T cell development and displayed an increased central memory phenotype of T cells in peripheral lymphoid organs." (PMID 34819502, 2021). "The efficacy of anti-cancer effector T cells is intimately linked to the presence or absence of CD4+CD25+FoxP3+ regulatory T cells (T regs), and interestingly, T reg depletion induces TLS." (PMID 34122434, 2021). "Furthermore, treatment with soluble GITRL reduces the suppression of Tregs and restores the proliferation of CD4+CD25− T cells in cancer." (PMID 33557842, 2021).
cancer (continued). "Collectively, our results indicated that transcriptional changes induced in CD4+ T cells by cancer cells may be reversible when the contact with cancer cells is discontinued." (PMID 34439305, 2021). "Hence, it follows that the amount of circulating CD4+CD25hiFOXP3+ Tregs is often elevated in cancer patients." (PMID 34943819, 2021). "TIMER results showed that PAFAH1B3 expression correlated with CD8+ T cell abundance in 27 cancers, CD4+ T cell abundance in 28 cancers, neutrophil abundance in 30 cancers, dendritic cell (DC) abundance in 30 cancers, macrophage abundance in 27 cancers, and B cell abundance in 29 cancers." (PMID 35187070, 2021). "However, despite the formal absence of class II MHC binding predictions, the two validated CD4 neoantigens from two human cancer patients, one for each patient, were correctly ranked at the top of neoantigens selected by VENUS." (PMID 34452005, 2021). "Recent studies have reported that resting memory CD4 T cells are closely related with the pathogenesis of various malignant tumors, including GC, and pointed out that they might be affected by the key genes." (PMID 33718213, 2021). "Treg accumulation in cancer could occur through different mechanisms such as an expansion of pre-existing Treg, conversion of conventional CD4+ T cells into Treg." (PMID 34771724, 2021). "Similarly, the genes involved in angiogenesis were elevated in CD4+ T cells after restimulation and co-culture with cancer cells." (PMID 34439305, 2021). "In this study, PAFAH1B3 expression was significantly correlated with CD8+ T cell abundance in 27 cancers, CD4+ T cell abundance in 28 cancers, neutrophil abundance in 30 cancers, DC abundance in 30 cancers, macrophage abundance in 27 cancers, and B cell abundance in 29 cancers." (PMID 35187070, 2021). "We found that the ratios (CD8+/CD4+ regulatory T cells, pro-/anti-inflammatory cytokines, and M1/M2 macrophages) were significantly higher in EP300-mutated than those in EP300-wild-type cancers in multiple cancer types (two-tailed Student’s t-test, p < 0.05)." (PMID 34616736, 2021). "Furthermore, activated CD4+T cells can differentiate into various T helper cells with different effector functions, such as response in cancer immunotherapy." (PMID 33968068, 2021). "Additionally, the number of CD4+ T cells co-cultured with MDA-MB-231 cancer cells was dramatically reduced compared to CD4+ T cells growing in the absence of cancer." (PMID 34439305, 2021). "CD4 T cell response has been widely overlooked in cancer immunotherapy, but recently gained more attention as Th1 and Th17 CD4 T cells have been shown to contribute to anti-tumoral immune responses by promoting CD8 T cell recruitment and activation or by secreting inflammatory cytokines." (PMID 34276686, 2021). "The CD4+/CD8+ ratio is a marker of cell-mediated immunity in cancer patients." (PMID 34488711, 2021). "In this model the CD4 T cells responsible for the immune memory response were highly potent and could support a strategy of dealing with the problem of cancer metastases by immunoprevention." (PMID 33665363, 2021). "CD4+ T cells have a key role in making the immune response to cancer." (PMID 34276383, 2021). "In addition to cytotoxic CD8+ T cells, CD4+ T cells play important direct and indirect roles in anti-cancer immunity and therefore are indispensable for vaccination approaches." (PMID 34305947, 2021). "This could lead to the induction of polarized CD4+Th 2 cells promoting the expansion of cancer cells at the expense of CD8+T cells." (PMID 35008550, 2021). "While in vivo activation by a high salt diet could theoretically activate CD4+T cells in cancer patients, a potential recommendation of a high salt diet as a practical application is impossible." (PMID 33918403, 2021).
cancer (continued). "CD8+ lymphocytes directly kill the cancer cells, while the CD4+ cells (Th1- and Th2-lymphocytes) provoke the immune response against cancer cells, producing pro-inflammatory cytokines, recruiting other immune cell and interacting with the B cells to induce antibody production." (PMID 33026575, 2021). "Induced pluripotent stem cell-based cancer vaccine could also reduce immunosuppressive CD4+ T regulatory cells." (PMID 34691034, 2021). "T-cells specific for multiple cyclin B1 specific CD4 T-cell epitopes could be expanded from both cancer patients and volunteer donors." (PMID 34526999, 2021). "Moreover, in mass spectrometry analysis performed on media collected from restimulated CD4+ T cells grown with cancer cells, the secreted cytokines and other factors such as IL-8, IL-6, CXCL1, and ICAM1 were found." (PMID 34439305, 2021). "A high CD4/CD8 ratio is correlated with a poor prognosis for cancer patients." (PMID 34638642, 2021). "The results showed that YTHDC2 expression was significantly positively correlated with the infiltration levels of CD8+ T cell, CD4+ T cell, neutrophil, myeloid dendritic cell, macrophage and B cell in five types of cancer, containing COAD, KIRC, LIHC, LUAD and PAAD." (PMID 34312987, 2021). "Although CD3+ TILs include a CD4+ subset, the direct evidence of CD4+ T cell association with cancer progress is not strong." (PMID 34553029, 2021). "It is indicated that the diversified CD4+ T cell cloning responses may reflect the diversification of neoantigens of cancer cells." (PMID 33301062, 2021). "In contrast, the trimethylation of K27 in H3 (H3K27me3) was detected only at the −17 bp position upstream of TSS in CD4+ T cells co-cultivated with cancer cells, while in control cells the enrichment for H3K27me3 was found in the +441 bp position downstream of TSS." (PMID 34439305, 2021). "The results indicated that P4HA2 was notably correlated with CD8+T cells in 11 cancer types, B cells and memory B cells in 12 cancer types, plasmacytoid dendritic cells and naïve CD4+ T cells in 13 cancer types, and CD4+Th1 cells in 17 cancer types (P < 0.0001)." (PMID 34249930, 2021). "If CD4+ T cells exhausted due to contact with cancer cells are separated from these cancer cells, they start to suppress the proangiogenic and cytokine-encoding genes and restore the expression of SWI/SNF CRC genes, resulting in the observed reduction of PD-L1 expression." (PMID 34439305, 2021). "CD4+ T cells are crucial for effective repression and elimination of cancer cells." (PMID 33542711, 2021). "Furthermore, the association was also observed for 9, 12, 24, 23, 21, and 24 cancer types, corresponding to the B cells, CD8+ T cells, CD4+ T cells, macrophages, neutrophils, and dendritic cells infiltration levels, respectively." (PMID 33306121, 2021). "Taken together, our study unravels a previously unappreciated CD4+ T cell-derived IL-21–BATF axis that could provide therapeutic insights to enhance effector CD8+ T cell function to fight cancer." (PMID 33809259, 2021). "Combinations of therapies that can drive multiple subtypes of CD4 TH may better overcome this inadequacy and improve therapeutic efficacy in cancer." (PMID 34012451, 2021). "For peptide-based cancer vaccines to make their mark on cancer treatment, future studies will need to ensure a robust combination of in vivo CD4+ and CD8+ responses in a package that strongly activates DCs and subsequently T cells in a prolonged fashion, with minimal exhaustion or immune tolerance." (PMID 34276688, 2021). "Moreover, we found that the exhaustion process is at least partially reversible when CD4+ T cells lose contact with cancer cells." (PMID 34439305, 2021). "Although the impact of targeting PSGL-1 specifically on CD4+ T cells will have on cancer metastasis is unknown, these studies illustrate that PSGL-1 presents an exciting target for potentially reducing metastatic behavior of tumors." (PMID 33708224, 2021).
cancer (continued). "CD4+ T cells are a key determinant of the immune status due to their essential role in orchestrating immune responses in autoimmune diseases, immune-mediated inflammatory diseases (IMIDs), cancer, and chronic viral infections." (PMID 34956237, 2021). "However, CD4+T-cells showed an essential role in initiating anti-cancer immune responses, which significantly affects the function of CD8+T-cells." (PMID 35201470, 2021). "It would be more interesting if high salt treatment on circulating CD4+T lymphocytes of human cancer patients could be similarly activated to exert anti-cancer effect." (PMID 33918403, 2021). "CD4+ FOXP3+ Tregs, a subset of CD4+ T lymphocytes, are highly related to cancer immunosuppression." (PMID 34502359, 2021). "According to the role of sB7-H5 in various cancers, it may have both coinhibitory functions in inhibiting the proliferation of human CD4 and CD8 T cells and the production of T cell cytokines or costimulatory functions in immune signalling." (PMID 34660778, 2021). "Interestingly, the binding of the second SWI/SNF ATPase, BRG1, to PD-L1 was found only for CD4+ T cells co-cultured with cancer cells." (PMID 34439305, 2021). "In addition, we found that the patients who experienced local radiation to the brain metastases before brain surgery observed a higher number of CD4+ T-cells in cancer areas and stroma of brain metastases." (PMID 34647108, 2021). "Higher ANXA4 expression significantly decreased CD4+ Th1 cells across 30 cancer types." (PMID 34540918, 2021). "Even though a large number of studies have focused on teasing out the role of neoantigen-targeted CD8+ T cell activity in cancer, significant and preferential CD4+ T cell activation by neoantigens have been recognized in multiple pre-clinical and clinical studies." (PMID 34012451, 2021). "We also used the xCell algorithm to further estimate the relationship between HSF2 expression and the level of infiltrating immune cells and found that HSF2 expression was significantly correlated with infiltrating CD4+ T helper (Th) cells and macrophages in most cancer types." (PMID 35087869, 2021). "Furthermore, the finding that the density of CD4+ T-cells was higher in cancer and stroma areas of brain metastases after radiotherapy supports the addition of immunotherapy to radiation therapy in the treatment of brain metastases in NSCLC." (PMID 34647108, 2021). "Considering the need for robust biomarkers in HNSCC and the contrasting evidence concerning TILs in this cancer group, the aim of this paper was to systematically review and perform a meta-analysis of recent evidence concerning the prognostic significance of CD4+ and CD8+ TIL populations in HNSCC." (PMID 33668519, 2021). "Therefore, in the diagnosis and treatment of malignant tumors, CD4+ T cells should be further examined." (PMID 34327142, 2021). "Correlation analysis showed that the infiltration levels of B cells, CD4+ T cells, and CD8+ T cells were negatively correlated with the SRS score, whereas a higher SRS score indicated increased abundance of neutrophils, cancer-associated fibroblasts, Tregs, and resting NK cells." (PMID 34869385, 2021). "However, the result revealed that none significant correlation was found between GPRC5A gene expression and CD4 + T cell, CD8 + T cell, B cell, NK cell, monocyte, macrophage cell, dendritic cell or cancer associated fibroblast infiltration in PADD." (PMID 34819098, 2021). "Therefore, reciprocal effects between TAMs and CD4+ or CD8+ T cells are expected in the cancer environment, but further investigations are needed for clarification." (PMID 34299098, 2021). "Interestingly, we found decreased levels of both Suz12 and EZH2 subunits in CD4+ T cells co-cultured with MDA-MB-231 cancer cells." (PMID 34439305, 2021). "However, these strategies must be critically guided by a deeper understanding of the biology of cytotoxic CD4+ T cells in human cancer." (PMID 34910940, 2021).
cancer (continued). "The results implied that HSF2 expression was markedly correlated with the infiltrating level of B cells in 16 types of cancer, CD4+ T cells in 12 types of cancer, CD8+ T cells in 16 types of cancer, macrophages in 17 types of cancer, neutrophils in 18 types of cancer, and DCs in 18 types of cancer." (PMID 35087869, 2021). "However, the CD4+ T cells/CD8+ T cell ratio was significantly lower in the PB of NSCLC patients with poor cancer cell differentiation." (PMID 35116020, 2021). "Recent studies have shown that cancer cells could secrete cancer-IgG into the TME that binds to sialic acid-binding immunoglobulin-type lectins (Siglecs) on effector CD4+ and CD8+ T cells." (PMID 34760705, 2021). "In summary, increased NAT10 expression was correlated with poor prognosis in 12 types of cancer, especially ACC, KIRP, LIHC, HNSC, and PCPG, and with increased immune infiltration levels of CD8+ T cells, CD4+ T cells, macrophages, neutrophils, and DCs in various cancers." (PMID 34094911, 2021). "When we expanded these results to other tumors and normal tissue types, we found ASF1B to be unrelated to gamma delta T cell or activated memory CD4+ T cell infiltration in normal tissues, and it was similarly unrelated to naïve CD4+ T cell infiltration in analyzed cancers." (PMID 34568067, 2021). "However, several studies demonstrate the potential impact of metformin on maintaining CD8+ TIL function and possibly enriching a high CD8+/CD4+ ratio to promote an immunoreactive environment in other cancers." (PMID 33467127, 2021). "Additionally, EZH2, a main PRC2 subunit, was located +219 bp and +441 bp downstream from TSS on the PD-L1 locus only for CD4+ T cells co-cultivated with cancer cells." (PMID 34439305, 2021). "CD8+ and CD4+ T cells are cytotoxic immune cells that directly or indirectly kill cancer cells." (PMID 34168096, 2021). "Among persons with NADC, factors associated with increased mortality were older age at cancer diagnosis, non-white race, nadir CD4 cell count < 200 cells/mm3, viral load ≥ 400 copies/mL, and prior or current history of tobacco use." (PMID 33670229, 2021). "In the present study, a combined HPV16 L1 gene methylation (≥20%) and a low percentage of a CD4 count might be beneficial to differentiate HIV-infected MSM who are at risk to rapidly progress to high-grade AIN and carcinoma." (PMID 34469465, 2021). "In addition, a higher number of CD4+ T-cells was observed in carcinoma and stromal areas of brain metastases after local radiotherapy to the brain, which was associated with longer overall survival (OS)." (PMID 34647108, 2021). "Because CD4+ T cells produce cytokines that induce glycolysis in cancer cells, this cellular composition may be an important factor affecting glycolysis of cancer cells." (PMID 32189078, 2020). "In conclusion, the results of the present study indicated that NFE2L2 overexpression correlates with poor prognosis of patients and increases the infiltration levels of B cells, CD8+ T cells, CD4+ T cells, macrophages, neutrophils, and dendritic cells in many cancers, especially in LGG." (PMID 33101586, 2020). "Besides, immune cells showed large differences in their populations in various cancers, and the most abundant cells were resting memory CD4 T cells." (PMID 32294976, 2020). "Activation of CD4 T-cells in a cancer microenvironment also impacts the immunity system." (PMID 32665773, 2020). "We analyzed the percentages of CD4+ and CD8+ T cells expressing the PD-1 marker, since the latter has been associated with T cell exhaustion in HIV-infected patients, as previously demonstrated in cancer patients." (PMID 33167335, 2020).